IL6 (interleukin 6)
Diseases named in the same sentence as IL6 in open-access papers (continued):
Sharing a sentence is not in itself a finding about the gene and the disease.
tumor (continued). "Relative concentrations of IL6 and TGFβ in tumor tissues balance the differentiation of coexisting CD4+ RORγt+ Th-17 cells and regulatory CD4+ FoxP3+ RORγt+ IL17-negative T cells." (PMID 34804993, 2021). "It has been demonstrated that IL-6 is involved in MDSCs infiltration of tumors leading to increased tumor progression." (PMID 35003065, 2021). "The results of the combined analysis of IL-6 and tyrosine kinase inhibitors (TKI) showed that high levels of IL-6 can upregulate the mTOR signaling pathway and induce tumor cell resistance to TKI therapy." (PMID 33582655, 2021). "Both local autocrine and paracrine release are able to activate IL6 trans-signalling, thus contributing to the cytokine’s tumour-promoting effects." (PMID 34834425, 2021). "USG was characterized by a high expression of interlekin-6 (IL-6), a gene involved in infection/inflammation that seems to play a pro-tumorigenic role, contributing to proliferation and invasion of the tumor cell." (PMID 35008342, 2021). "IL-6 does not only exhibit tumor cell-intrinsic activities but also tumor cell-extrinsic activities." (PMID 34671021, 2021). "IL6 can activate oestrogen-generating enzymes in both the tumour and adjacent tissues, acting as a key modulator of the conversion of estrone to estradiol." (PMID 34834425, 2021). "One example is the secretion of IL-6 by tumor cells that leads to STAT3 activation in LECs and subsequently high VEGF expression." (PMID 33922795, 2021). "Mast cells can release various proangiogenic factors, such as VEGF, FGF-2, PDGF, IL-6, tryptase, and chymase, to promote tumor angiogenesis and induce neovascularization." (PMID 34613934, 2021). "Observed reduction of IL-1β and IL-6 expression at the genetic level in tumour lesion are consistent with those of previous studies." (PMID 33658555, 2021). "In vivo, IL-35 has been demonstrated to promote tumor growth, progression and metastasis by enhancing the secretion of other cytokines, such as IL-6 and G-CSF (granulocyte colony stimulating factor)." (PMID 34093586, 2021). "The overexpression of gastrointestinal inflammatory cytokines such as IL-6 and IL-17 increases the severity of the tumor." (PMID 34194957, 2021). "In brief, the two main ways of IL-6 are not limited to intestine but also in various kinds of cancers, here, we just summarize the researches of IL-6 and its tumor-related functions specifically in the gut." (PMID 33390844, 2021). "Our ELISA results in animal model showed a positive correlation of plasma IL-6 level with tumor size." (PMID 34093869, 2021). "IL‐6 is produced by several bone‐homing cancer cells, where it facilitates bone invasion and growth of tumor cells in the bone microenvironment." (PMID 33869989, 2021). "Accordingly, in mouse models of colorectal and ovarian carcinoma, the inflammatory response of tumor and immune cells involves IL-6 production that can stimulate platelet production by enhancing TPO secretion from hepatocytes." (PMID 34322381, 2021). "Tumours from Osm−/− animals exhibited markedly reduced levels of several cytokines, including IL6, CXCL1, GM-CSF and TNFα, highlighting a profound change in the tumour environment." (PMID 34921158, 2021). "IL-6 can be expressed at high levels in the tumor microenvironment and is a major mediator of inflammation." (PMID 34445405, 2021). "Taken together, these data suggest that combination therapy with immunogenic chemotherapy, manipulation of the tumor microenvironment through IL-6 inhibition, and checkpoint blockade is a promising therapeutic approach for treating human cancer." (PMID 34711820, 2021). "Our and previous results suggest that IL6 is a potential mediator of crosstalk between tumor cells and BMSC in NB." (PMID 34790130, 2021). "Unexpectedly, genetic inactivation of STAT3 or IL-6 in prostate-specific PTEN knock-out mice led to accelerated tumour progression and metastasis." (PMID 34047814, 2021).
tumor (continued). "For example, in pancreatic ductal adenocarcinoma, CAFs mediate the exosomal metastasis and paracrine of tumor cells through producing cytokines (such as GM‐CSF and IL‐6), and this process requires the participation of NF‐κB." (PMID 34977871, 2021). "In cancer, IL-6 appears to have a dual role of either driving tumor growth or promoting anti-tumor immunity." (PMID 34214127, 2021). "Compelling reports have demonstrated that IDO promoted the IL-6 expression in tumor cells, and in turn, IL-6 was reported to upregulate IDO expression through a JAK/STAT signaling pathway." (PMID 34657635, 2021). "Pro-inflammatory cytokines (e.g. TNF-α, IL-6), particularly in chronic inflammation, can lead to reactive oxygen species-derived DNA-damage, resulting in tumor promotion." (PMID 33628623, 2021). "The correlation analysis revealed that IL6 expression was mainly negatively correlated with the probesets methylation in most tumor types." (PMID 34576335, 2021). "Tumor angiogenesis is strongly promoted by CAFs through the production of immunomodulatory and pro-angiogenic chemokines and cytokines like IL-4, IL-8, IL-6, TNF, CXCL12, TGFβ and VEGF." (PMID 33472580, 2021). "Gene silencing of MEST, a key regulator of IL-6/JAK/STAT3/Twist-1 pathway-mediated tumour metastasis, has been demonstrated in other sarcomas and concordantly, we observed hypomethylation for the DMR containing MEST in one of our sets." (PMID 33436720, 2021). "Consistently, suppression of STAT3 and NF-kB reduced the proliferation and colony formation of IL-6 treated tumor cells." (PMID 34657635, 2021). "Factors that induced MDSC in mice models of uterine endometrial and cervical cancer include tumor-derived G-CSF, IL-6, estradiol (E2), and Swainsonine." (PMID 33946532, 2021). "As inflammation progresses, it promotes the production of tumor-promoting cytokines such as IL-11, IL-1β, and IL-6, which support the survival, growth, and metastasis of tumor cells." (PMID 34150765, 2021). "We demonstrate a previously unrecognized tumor microenvironment mechanism by which paracrine IL6/IL8-JAK2 signaling induces BRD4 activation in CRC, leading to chromatin remodeling and resistance to BETi treatment." (PMID 34290255, 2021). "Combined with tumor stage data, the results suggested that IL-6 expression was significantly decreased in low-stage tissues compared with higher-stage tissues." (PMID 34881181, 2021). "Studies have shown that beta-sitosterol can inhibit cell proliferation in transplanted tumours in mice by inhibiting the expression of IL-6, TNF and VEGF." (PMID 35069454, 2021). "If the patients were grouped by tumor size, the IL-6 values in particular predicted survival among patients with medium-sized tumors (tumor diameter from 4 to 7 cm) (p = 0.018), but not statistically significant (p = 0.063) among large tumors." (PMID 32621022, 2021). "The observation of increased IL6 levels in OC ascites at levels 100 times higher than the serum/plasma levels further suggests IL6 involvement in OC progression within the tumor microenvironment." (PMID 34945807, 2021). "We further detected the expression patterns of miR-155-5p, ZC3H12B, and IL-6 in tumor tissues of mice." (PMID 33718596, 2021). "In common with IL-6, it is responsible for the growth and proliferation of tumor cells and for enhancing their immune escape mechanisms." (PMID 34830096, 2021). "Ablation of XBP1 inhibited the expression of the pro-tumor cytokine signature of TAMs, including IL-6, VEGFA, and IL-4." (PMID 34667145, 2021). "Although tumor inoculation of the 4T1 cell line generated greater levels of TNF-α, IL-1β, IL-6 in the spleen, serum, primary tumor, and liver, the IL-1β cytokine increased only in the cortex and hippocampus." (PMID 34572719, 2021). "Through all three ways of trans signaling, IL-6 promotes the growth of cancer cells, whereas STAT3 IL-6 also promotes tumor cells’ ability to escape apoptosis." (PMID 32621022, 2021).
tumor (continued). "The A375SM-TECs showed a significantly higher level of IL-6 than A375 tumor-derived TECs (A375-TECs) or mouse normal dermis-derived ECs (NECs)." (PMID 34226586, 2021). "In samples taken from the tumour tissue, the RQ values of IL-1β and IL-6 were higher in patients with pT1 stage vs. pT3 stage, while those of IL-17 were higher in pT3 vs. pT2 patients." (PMID 33658555, 2021). "As the prototypical pro-tumourigenic member of its cytokine family, IL6 has been shown to exert a wide range of pro-cancer effects, including promoting tumour initiation and progression, survival, invasion, metastasis and chemo-resistance." (PMID 34834425, 2021). "The role of cytokines such as interleukin (IL)-6 has been described in the NB microenvironment promoting tumor progression and metastasis." (PMID 33573284, 2021). "Tr1 cells are immunosuppressive and downregulate the cytotoxic activity of CD8+ T cells and NK cells, as well as preventing the production of TNF-α and IL-6 by monocytes, which are important for anti-tumor immunity." (PMID 33418929, 2021). "Uptake of tumor-derived exosomes also alters the cytokine secretion (IL-6, IL-1β, IL-10 and TNFα) of macrophages thereby facilitating several pro-tumoral functions." (PMID 34638420, 2021). "Cytokines including TNF-α, IFN-γ, IL-2, IL-6, and IL-12 were also increased in the PB and in tumour lesions of mice with P@aPDL1 and Vadimezan treatment." (PMID 33986264, 2021). "gaMSCs secrete several cytokines and exosomes into the tumour microenvironment, such as IL-6, CCL-5 and VEGFA." (PMID 34256854, 2021). "Anti-IL-6 therapy neutralizes IL-6 and inhibits the proliferation of tumor cells in early-stage diseases." (PMID 33495421, 2021). "The proinflammatory cytokine IL-6 is likewise an important contributor to tumor growth and progression." (PMID 34359685, 2021). "IL-6, as an important immunosuppressive and immunosuppressive cell recruitment factors, has a profound effect on immune cell infiltration in the tumor immune microenvironment." (PMID 34034744, 2021). "Increased levels of the anti-inflammatory cytokines IL-6 and IL-10 were also noted in co-cultures of single-cell tumor suspensions with PBMC and C-7." (PMID 34771609, 2021). "The team showed IL‐6 production by tumour EV‐educated mesenchymal stem cells (TEMSC) to be responsible for stimulating tumour growth." (PMID 33145869, 2021). "Previous studies have shown that tumor-derived soluble mediators, e.g., IL-6, TGF-β, and CCL2 can significantly suppress DC’s functions and impair their ability to initiate antitumor immune responses." (PMID 33568170, 2021). "Our group previously revealed that tumour‐associated macrophages (TAMs) secrete IL6 to promote EMT; mesenchymal tumour cells, in turn, enhance the recruitment of TAMs, which form a positive feedback loop and consequently induce liver metastasis." (PMID 34936736, 2021). "IL-6/STAT3 signalling has been shown to play an important role in tumor progression in many solid tumor types by inducing epithelial-to-mesenchymal transition and angiogenesis." (PMID 33806019, 2021). "IL-6 in tumor biopsy tissue is a biomarker for the diagnosis of cancer cachexia, and tumor cells are an important source of IL-6." (PMID 34863141, 2021). "MiR-21 knockout mice which received AOM/DSS presented a reduction of neoplasms size and numbers and induced inflammatory and carcinogenic cytokines such as IL-6, IL-17A, IL-21, and IL-23." (PMID 33921348, 2021). "Sunitinib inhibited MamBo38HER2loss tumor growth in vivo and reduced stemness and IL6 production in vitro." (PMID 34775465, 2021).
tumor (continued). "CAFs are prolific producers of soluble factors implicated in tumor immunosuppression such as transforming growth factor beta (TGF-β), indoleamine-2,3-dioxygenase (IDO), prostaglandin E2 (PGE2), interleukin-6 (IL-6), tumor necrosis factor a (TNF-α), and VEGF." (PMID 35082797, 2021). "IL-6 itself is known to be involved in several processes that favor tumor progression like, e.g., regulation of apoptosis, survival, proliferation, angiogenesis, metabolisms, and invasion of tumor cells." (PMID 33808494, 2021). "The knockdown of GPR68 or the inhibition of IL-6/STAT3 pathway in MSCs suppress in situ tumor growth and prolong lifespan after cancer grafting." (PMID 34681692, 2021). "Immune suppression is further mediated through the secretion of factors such as TGF-β, IL-10, VEGF, and IL-6 by cancer cells and other cells present in the tumor." (PMID 34671021, 2021). "Overexpression of p16 in tumor cells and stromal fibroblasts contributes to tumor progression by secreting proinflammatory cytokines (IL-1, IL-6 and IL-8) and proteases (e.g., matrix metalloproteinases)." (PMID 34575014, 2021). "An emerging research field deals with the understanding of the tumor cell response to IL-6 taking into account the precise regulation of IL-6 receptor complex consisting of IL6-R and gp130 proteins, which also exists in membrane-bound and/or soluble forms." (PMID 34576335, 2021). "IL-6, produced by tumors or tumor-infiltrating cells, binds to its target receptor IL-6R and leads to Jak2/STAT3 activation." (PMID 34833950, 2021). "For example, we and others have demonstrated that cytokines released by CAFs, including C‐X‐C motif chemokine 12, transforming growth factor‐β, IL‐6, and IL‐8, induce tumor metastasis and chemoresistance." (PMID 34363355, 2021). "Subsequently, the lysis of tumor cells has been shown to activate macrophages, which release a large amount of inflammatory factors (e.g., IL-6 and IL-1), inducing CRS." (PMID 34248142, 2021). "Based on its pro-tumor effects, many primarily developed pharmaceuticals with completely IL-6 blockade were tested and used." (PMID 33390844, 2021). "Numerous evidences have shown that IL-6 induces the migration and invasiveness of different types of tumor cells and therefore represents a prognostic factor related to cell survival." (PMID 34885656, 2021). "These clinical data together support our experimental results showing that IL-6 controls CD40 expression in GBM-associated Mφs, and that IL-6 and CD40 critically regulates tumor immunity and determine pathological outcomes." (PMID 34103524, 2021). "OS cells cause the upregulation of IL-6 and VEGF in MSCs, thereby maintaining their stemness, which supports tumor growth and migration." (PMID 34681692, 2021). "While periglandular αSMAhigh myofibroblastic CAFs likely restrain tumor growth, diffusely distributed αSMAlow IL-6–positive inflammatory CAFs promote tumor growth possibly by secreting ECM and cytokines such as IL-6." (PMID 34253690, 2021). "The polysaccharide fraction also reduced vessel areas, promoted necrosis, and increased IL-6 in the tumor tissue." (PMID 34200897, 2021). "Although IL-6 deficiency did not affect esophageal tumorigenesis in mice, there are less vessels in the tumor tissue of 4NQO-induced IL-6 KO mice than that in 4NQO-induced wildtype mice." (PMID 34393797, 2021). "In melanoma, the BRAF V600E mutation is linked to increased STAT3 activity and increased expression of IL-1, IL-10, and IL-6, which in turn influence dendritic cell activity within the tumour microenvironment." (PMID 33669775, 2021). "Long-lived pro-tumor neutrophils were also observed when exposed to IL-6 produced by cancer-derived mesenchymal stem cells." (PMID 34572138, 2021). "In fact, apart from the well-known role in inflammation and tumor which we will discuss in part 3 and 4, IL-6 is required for tissue repairing after injury for its induction of intestinal epithelial proliferation." (PMID 33390844, 2021).
tumor (continued). "In the tumor stroma, CAFs secrete the cytokines CXCL1 and CXCL2 as well as the interleukin-6, which promote angiogenesis and tumor progression." (PMID 33806312, 2021). "IL-6 is a pro-survival signaling molecule released by non-tumor cells harboring or surrounding the tumor microenvironment." (PMID 34551797, 2021). "DCs are recruited to infected tumors following S. Typhimurium administration, and those isolated from the tumor‐draining LNs produced more IL‐6, TNF‐α, and IL‐1β than DCs harvested from control mice." (PMID 34633664, 2021). "As well, BC cells can upregulate IL-6 expression in adipocytes, which in turn promotes angiogenesis, tumor cell proliferation and survival via the Janus kinase/signal transducer and activator of transcription 3 (JAK/STAT3) signaling pathway." (PMID 34638283, 2021). "In turn, osteoblasts produce growth factors that further stimulate tumor growth, such as interleukin-6 (IL-6), monocyte chemoattractant protein 1 (MCP-1), or vascular endothelial growth factor (VEGF)." (PMID 34439218, 2021). "A previous study reported that HSP90 is involved in activating the IL6/JAK/STAT3 signaling pathway to affect tumor progression." (PMID 34712697, 2021). "As IL-6 is involved in tumor angiogenesis, it affects the development and progression of the tumor by promoting the development of ascites." (PMID 34572929, 2021). "In Cr(VI)-induced carcinogenesis, miR-143 inhibits tumor growth and angiogenesis by regulating IL-6/HIF-1α in vivo." (PMID 34211501, 2021). "Elevated expression of phosphorylated STAT3 and NF-kB/TIM4 was observed in tumor cells after IL-6 stimulation." (PMID 34657635, 2021). "In non-small cell lung cancer, cisplatin induces IL6 secretion that increases tumor progression and resistance to treatment through up-regulation of anti-apoptotic proteins and DNA repair associated genes." (PMID 34447383, 2021). "It is therefore not surprising that combination of anti-PD-1 antibodies with anti-IL-6 antibodies impairs the immunosuppressive tumour micro-environment and is a promising strategy also for the therapy of HCC." (PMID 34047814, 2021). "It has been reported that different cell types in the tumor niches produce IL-6, and the IL-6/JAK/STAT3 pathway is aberrantly hyperactivated in many cancers, leading to the increased tumor-cell growth and progression, survival, and metastasis." (PMID 33461943, 2021). "To identify the sources of IL-6 and sIL6R, we measured Il6 and Il6r mRNA expression in muscle, fat, liver, and tumor." (PMID 33851955, 2021). "IL-6 signaling also plays a role in maintaining the tumor stem cell niche and stimulating angiogenesis." (PMID 34222022, 2021). "Th1 cells secrete cytokines IFN-γ, TNF-α, IL-12, which play an essential role in tumor immunity, and IL-4, IL-6, and IL-10 are cytokines secreted by Th2 cells, which can inhibit the secretion of cytokines by Th1 cells and promote humoral immunity." (PMID 35071004, 2021). "It seems that enhanced concentration of IL-6 significantly promotes the viability and proliferation of tumor cells." (PMID 33478512, 2021). "IL-6 has also been shown to be overexpressed by several types of tumor tissues and can play an important role in various aspects of tumor behavior, including apoptosis, proliferation of tumor growth cells, migration and invasion, angiogenesis, and metastasis." (PMID 34885171, 2021). "Studies have reported that IL-6 produced by tumors is involved in accumulation and expansion of MDSCs in tumor-bearing hosts." (PMID 34578883, 2021). "We assumed that A375SM cell-derived factors induced IL-6 upregulation in A375SM-TECs in tumor microenvironment." (PMID 34226586, 2021). "Although less remarkable, two-way ANOVA demonstrates a significant effect of the tumor on the hepatic gene expression of IL-6." (PMID 34445729, 2021). "In vivo, MIBC mouse models were treated with IL-6 for the analyses of tumor growth rates and tumor weights." (PMID 33981768, 2021).